FGF23 (fibroblast growth factor 23)
Diseases named in the same sentence as FGF23 in open-access papers (continued):
Sharing a sentence is not in itself a finding about the gene and the disease.
renal dysfunction (28 papers, 2013 to 2025). "FGF-23 is one of the most important components of mineral and bone metabolism and its excess is linked to the progression of renal dysfunction." (PMID 35216382, 2022). "Though, renal dysfunction explains most, or all, of the association between FGF23 and CVD mortality." (PMID 23587028, 2013). "In addition, renal dysfunction was associated with significant elevations in the plasma levels of both intact FGF23 (353 ± 58 vs. 7382 ± 2014 pg/mL, p < 0.05) and c-terminal FGF23 (187 ± 34 vs. 3075 ± 858 pg/mL, p < 0.05)." (PMID 38673780, 2024). "The aim of this study was to evaluate the correlation of FGF‐23 with parameters of renal dysfunction in dogs and cats." (PMID 38053473, 2023). "IR injury-induced renal dysfunction was accompanied by an increase in the fractional excretion of Ca2+ and by an impairment in the balance of the fibroblast growth factor 23-klotho-vitamin D axis through down regulation of Klotho expression." (PMID 35155498, 2022). "Most epidemiological studies assessing the relationship between circulating levels of FGF23 or α-Klotho and cardiac abnormalities have been performed among a population that either exclusively has renal dysfunction or includes many such subjects." (PMID 27400031, 2016). "Even after adjusting for preexisting cardiac or renal dysfunction, FGF23 remained a significant and independent predictor of duration of surgery, duration of cardiorespiratory support and the time of hypothermic circulatory arrest." (PMID 25902817, 2015). "It seems possible that calcidiol and also FGF-23 levels are more direct markers of the abnormalities leading to cardiovascular damage in renal dysfunction than glomerular filtration rate." (PMID 24748388, 2014). "Therefore, a potential influence of postprandial state and diet composition on the concentrations of the parameters of renal dysfunction and FGF-23 concentrations is possible." (PMID 37889764, 2023). "This is contradicting to our results, but may be partly explained by overestimations of T score in the lumbar spine as well as the potential impact of renal dysfunction as pre-HT levels of FGF23 correlated with both measured and estimated GFR pre-HT." (PMID 36148003, 2022). "In developed renal dysfunction, FGF23 levels increase to maintain the phosphate excretion capacity." (PMID 27504998, 2016). "Patients with less severe renal dysfunction also have elevated FGF23." (PMID 26019137, 2015). "However, it is completely unknown whether FGF23 is also involved in type 2 CRS (chronic heart failure leading to renal dysfunction)." (PMID 33460402, 2021). "In addition, it was found that serum FGF23 was significantly associated with LVEF among patients with CKD stages G1/G2 and G3a; unexpectedly, however, the relationship was insignificant among patients with more severe renal dysfunction (CKD G3-G5)." (PMID 27400031, 2016). "Fibroblast growth factor 23 (FGF23) is increased in both renal dysfunction and cardiac dysfunction, and FGF receptor 4 (FGFR4) has been identified as a receptor for FGF23." (PMID 33460402, 2021). "In a few studies, on the other hand, the relationship between FGF23 and cardiac abnormalities or cardiovascular outcome has been studied in patients without renal dysfunction or with relatively preserved renal function." (PMID 27400031, 2016). "The present study aimed to assess the predictive role of FGF-23 for clinical outcome in a large cohort of CS patients with and without renal dysfunction." (PMID 25528363, 2014). "Decreased renal clearance due to renal dysfunction, in addition to higher synthesis in the liver, thymus, spleen, and bone due to non-classic regulators of FGF23 production (PTH, vitamin D, and phosphate), would explain the acute increase in plasma FGF23 in AKI." (PMID 37892163, 2023).
renal dysfunction (continued). "Finally, to elucidate the contribution of Klotho to the prolongation of ventricular repolarization beyond renal dysfunction, we examined ECG parameters in mice hypomorphic for Klotho (kl/kl), which show very high systemic levels of FGF23, and in wild-type (+/+) littermates." (PMID 35042527, 2022). "In addition, by increasing overall study sample, we could statistically analyze the association, or non-association, between FGF23/α-Klotho and LVH/low LVEF among the patients with various subcategories (i.e., CKD stage G3a, G3b, and G4) of renal dysfunction." (PMID 27400031, 2016).
Hypercalciuria (26 papers, 2007 to 2025). "Their phenotype associate hypercalcemia, hypercalciuria, a rise in 1,25(OH)2D and a decrease in FGF23 serum concentrations." (PMID 36596813, 2023). "In the HHRH patients, hypercalciuria is associated with high 1,25(OH)2D serum concentration and low FGF23 level in the plasma." (PMID 36596813, 2023). "A defect in one of these genes leads to hypercalciuria consequent to primary phosphate loss in the kidney, followed by downregulation of FGF23." (PMID 34858904, 2021). "FGF23-independent causes of hypophoshataemia are alcohol abuse, drugs or toxins, renal tubular acidosis, Fanconi’s syndrome or hereditary hypophosphatemic rickets with hypercalciuria." (PMID 27709474, 2016). "Disorders such as Fanconi syndrome and hereditary hypophosphatemic rickets with hypercalciuria constitute the differential diagnosis when renal phosphate leak is accompanied by low FGF-23." (PMID 39055417, 2024). "Further evidence supporting biologic actions of high 1,25-vitamin D included changes in renal Cyp24a1, Trpv5, and Calbindin D28k expression; circulating intact and C-terminal FGF23 levels; and hypercalciuria." (PMID 36862513, 2023). "Based on these observations, the aim of this study was to explore the possible role of FGF23 in children with hypercalciuria." (PMID 29457024, 2017). "In the FGF23-independent HR group, hypercalciuria and nephrolithiasis are major clinical findings and oral phosphate replacement alone is sufficient in the treatment." (PMID 29280738, 2017). "Plasma FGF23 was measured in 29 controls and 58 children and adolescents with hypercalciuria: 24 before treatment (Pre-Treated) and 34 after 6 months of treatment (Treated)." (PMID 29457024, 2017). "This study explored the possible role of FGF23 in pediatric hypercalciuria." (PMID 29457024, 2017). "In the present study, we explored the possible role of FGF23 in pediatric hypercalciuria." (PMID 29457024, 2017). "It was suggested that variations in the klotho-FGF23 axis could mediate alterations in phosphate handling by the kidney and thus play a role in hypercalciuria, and indeed a few studies in adult calcium stone formers reported higher fibroblast growth factor 23 (FGF23) levels." (PMID 29457024, 2017). "Therefore, a patient with a presumed diagnosis of XLH presenting with hypercalciuria should never be started on conventional treatment (phosphate supplements and active vitamin D) or burosumab—an FGF23 antibody—as this may promote progressive nephrocalcinosis." (PMID 34910242, 2022).
congestive heart failure (23 papers, 2013 to 2025). Failure of the heart to pump a sufficient amount of blood to meet the needs of the body tissues, resulting in tissue congestion and edema. "Recently, data from 382 patients enrolled in the TIME-CHF (Trial of Intensified vs. Standard Medical Therapy in Elderly Patients With Congestive Heart Failure) cohort have questioned the role of FGF23 in risk stratification." (PMID 37658340, 2023). "Importantly, recent observational studies have shown strong associations between elevated FGF23 and greater risk of cardiovascular events, particularly congestive heart failure, in patients with chronic kidney disease, hemodialysis patients, and individuals with apparently normal kidney function." (PMID 34765890, 2021). "Previous studies have also shown that high FGF-23 levels in CKD were independently associated with PH, LVH, chronic heart failure, and higher mortality." (PMID 36790465, 2023). "In chronic heart failure, phosphate and fibroblast growth factor-23 (FGF-23), which are important components of the vascular calcification pathway, have been linked to patient survival." (PMID 34222283, 2021). "Cross-sectional studies have revealed that higher plasma or serum FGF-23 is associated with LVH in CKD, which can lead to congestive heart failure and subsequent death." (PMID 34336893, 2021). "In unadjusted Cox models, the HR [95% CI] for hospitalization for congestive heart failure (comparing the highest FGF23 quartile with the lowest FGF23 quartile) was 8.18 [5.47‒12.24], and the association remained statistically significant after adjustment in many different multivariable models." (PMID 29874852, 2018). "In this study we show that FGF23 rather than sKlotho in the serum is associated with disease severity and progression of chronic heart failure." (PMID 29849175, 2018). "However, when FGF23 concentration increases, as observed when renal function declines or in chronic heart failure, FGF23 can activate different signaling pathways that are Klotho-independent." (PMID 23825530, 2013). "Our results support the notion that FGF23 is upregulated in diseased human CMP hearts and might contribute to increased serum levels in chronic heart failure even prior to detoriation of renal function." (PMID 29849175, 2018).
fibrous dysplasia (21 papers, 2010 to 2026). A genetic, non-inheritable disorder caused by osteoblastic differentiation defects that result in the replacement of bone marrow and trabecular bone by fibrous stroma and immature bone. "The forms of HR caused by the excess of FGF23 are the X-linked form (XLH) caused by an inactivating mutation in the PHEX gene, tumor-induced osteomalacia (TIO), epidermal nevus syndromes, and fibrous dysplasia in McCune–Albright syndrome." (PMID 34208131, 2021). "Fibrous dysplasia (FD) is due to activating mutations in GNAS observed in McCune-Albright syndrome (MAS), which is characterized by FD of bone, café-au-lait spots, and precocious puberty, resulting in increased FGF23-synthesis in bone." (PMID 34910242, 2022). "The consequences of FGF23 on survival in other rare bone diseases that involve FGF23, such as fibrous dysplasia and cutaneous skeletal hypophosphatemia syndrome, are also unknown." (PMID 31730177, 2020). "Furthermore, high serum levels of FGF23 have been detected in patients affected by fibrous dysplasia (FD) of bone, which is a skeletal disorder with bone-forming cells failing to mature and aberrantly produce fibrous, or connective, tissue." (PMID 30374308, 2018). "Our patient did not have fibrous dysplasia nor café-au-lait spots as could be found in Mc Cune-Albright syndrome, which can also associated with elevated levels of FGF23." (PMID 39888445, 2025). "In addition, mosaic disorders with excess FGF23, such as fibrous dysplasia, McCune-Albright syndrome, and cutaneous skeletal hypophosphatemia syndrome, will also show suppressed FGF23 expression in nondysplastic bone." (PMID 39963340, 2025).
renal osteodystrophy (21 papers, 2014 to 2025). Abnormalities of bone mineral metabolism associated with chronic kidney disease. "After transplantation, the persistence of secondary and tertiary hyperparathyroidism, renal osteodystrophy, relative choleciferol deficiency and a high level of fibroblast growth factor-23 (FGF-23) contribute to PTBD." (PMID 38339137, 2024). "Compared with healthy volunteers, these 6 patients with ESRD have significantly elevated serum PTH and FGF23 levels, suggesting the high bone turnover renal osteodystrophy." (PMID 39883525, 2025). "As expected, CKD mice had markedly elevated PTH and FGF23 levels, suggesting the high bone turnover subtype of renal osteodystrophy in this model." (PMID 39883525, 2025). "We also confirm prior observations of increased serum FGF-23 levels in patients with high-turnover renal osteodystrophy and better bone mineralization with very high FGF-23 levels." (PMID 36970967, 2023). "Vitamin D, parathyroid hormone (PTH), and fibroblast growth factor-23 (FGF-23) are biomarkers of renal osteodystrophy." (PMID 36012420, 2022). "CKD-MBD begins early in the course of kidney disease and consists of renal osteodystrophy, vascular calcification (VC), and cardiac disease together with elevations of plasma phosphate (P) and fibroblast growth factor 23 (FGF23) as well as decrease of klotho." (PMID 31236663, 2019). "Nevertheless, it would be interesting to also study FGF23 expression in the bone of our mice since increased expression levels have been described recently in the bone of CKD patients with renal osteodystrophy." (PMID 29387084, 2017). "Unfortunately, currently available biomarkers such as PTH, FGF23, and alkaline phosphatase can only poorly predict the respective form of renal osteodystrophy and are of limited use in guiding therapy." (PMID 29387084, 2017). "In the current study, we examined the relationship between FGF-23 levels and bone histomorphometry parameters in adult patients with renal osteodystrophy." (PMID 25208316, 2014). "Interestingly, although exercise prevented trabecular loss, it did not alter serum PTH and FGF23 levels or the number of osteoclasts around trabeculae, suggesting that exercise does not alter the subtype of renal osteodystrophy." (PMID 39883525, 2025). "Thus, the expression of sclerostin in jck mouse, a model of progressive kidney disease occurs at early stages of CKD, even before PTH and FGF-23 increase, suggesting that sclerostin may play an early role in the development of renal osteodystrophy." (PMID 36615824, 2022). "In our latest study, we established a rat model of renal osteodystrophy and found that serum levels and bone expression of FGF-23 were both significantly elevated in uremic rats; and moreover, serum FGF-23 was negatively correlated with bone Col-X." (PMID 32517762, 2020). "It has been reported that renal osteodystrophy persists after transplantation because of elevated levels of PTH and fibroblast growth factor 23 (FGF-23), though at lower levels compared to pretransplantation." (PMID 26649301, 2015). "Further studies are necessary to evaluate the role of FGF-23 and the RANK/RANKL/OPG system in renal osteodystrophy and define if new medications, used to improve bone quality in non-dialysis patients, could influence bone turnover and mineralization in HD patients." (PMID 39768249, 2024).
Sepsis (21 papers, 2018 to 2025). Sepsis is defined as life-threatening organ dysfunction caused by a dysregulated host response to infection. "Assessing inflammatory factors as mediators between metabolites and sepsis, we found that while Docosadienoate (22:2n6) was correlated with sepsis, it was also associated with FGF-23 and OSM." (PMID 39205680, 2024). "Evidence from patients with CKD suggests an association between raised FGF23 levels and increased susceptibility to line infections, sepsis, and mortality." (PMID 36829583, 2023). "The present study demonstrated for the first time that CLP-induced sepsis causes a profound increase in circulating intact FGF23 in mice." (PMID 33989306, 2021). "In other words, why was sepsis associated with an apparent renal FGF23 resistance?" (PMID 33989306, 2021). "In our ICU cohort, serum KIM-1 predicted AKI and showed greater diagnostic discrimination than both iFGF23 and cFGF23, consistent with a prospective sepsis cohort in which KIM-1 showed a higher AUC than FGF23." (PMID 41152128, 2025). "They successfully measured the elevation of FGF23 protein amount in a polymicrobial sepsis model or an LPS-induced sustained inflammation model, where the elevation was 6-fold in the bone and 15-fold in the spleen, respectively." (PMID 38530370, 2024). "Blocking the erythropoietin receptor prevented the induction of bone marrow FGF23 and reduced the increase in plasma FGF23 in hemorrhagic shock or sepsis-induced AKI rodent models." (PMID 38496297, 2024). "Inflammatory factors such as AXIN-1, FGF-19, FGF-23, IL-4, and OSM were negatively causally associated with sepsis, while IL-2 was positively associated." (PMID 39205680, 2024). "In our study, we identified several inflammatory factors, including FGF-19, AXIN1, FGF-23, IL-4, OSM, and IL-2, that showed statistically significant associations with sepsis risk using the IVW method in MR analyses." (PMID 39205680, 2024). "In sepsis, FGF23 expression and secretion can be induced by cytokines and by signals triggered by renal hypoxia, such as glycerol-3-phosphate and EPO." (PMID 37892163, 2023). "Some studies report the increase of FGF23 in subjects with inflammatory diseases (eg, acute inflammation/sepsis, rheumatoid arthritis and childhood inflammatory bowel disease)." (PMID 36440231, 2022). "In the current study, we used the cecal ligation puncture (CLP) procedure to investigate further the role of FGF23 in the pathophysiology of sepsis." (PMID 33989306, 2021). "Nevertheless, reduced Klotho protein expression is one of the most likely scenarios for the renal FGF23 resistance observed in septic patients and experimental sepsis models." (PMID 33989306, 2021). "Hemorrhagic shock and sepsis-induced AKI in rats result in EPO-EPO receptor-dependent upregulation of Fgf23 mRNA levels in the bone marrow." (PMID 30405444, 2018). "We identified 36 metabolites significantly associated with sepsis (p < 0.05), with AXIN1, FGF-19, FGF-23, IL-4, and OSM showing an inverse association, suggesting a protective role, while IL-2 exhibited a positive correlation, indicating a potential risk factor." (PMID 39205680, 2024). "The bone appears to be the major source of FGF23 in acute CLP sepsis." (PMID 33989306, 2021). "This warrants further studies aimed at delineating the pathophysiological role of FGF23 in sepsis." (PMID 33989306, 2021). "Thus, our data support the notion that the bone is the major site of FGF23 expression in CLP-induced polymicrobial sepsis." (PMID 33989306, 2021). "In our current study, we found that sepsis patients had increased blood FGF-23 levels." (PMID 31791247, 2019). "Moreover, the correlation of sepsis with serum FGF23 (P = 0.068), urinary IGFBP-7 (P = 0.350), and urinary CysC (P = 0.391), however, did not remain significant after adjustment for age, body weight and illness severity in a multivariate analysis." (PMID 29907141, 2018).